INSR (insulin receptor)
Diseases named in the same sentence as INSR in open-access papers (continued):
Sharing a sentence is not in itself a finding about the gene and the disease.
type 2 diabetes (continued). "In fact, signaling downstream of the insulin receptor is very likely differentially affected in hearts of type 1 and type 2 diabetes as well, which may have deleterious effects on cell growth, cell survival and other cellular pathways." (PMID 27999359, 2016). "Additionally, resistance training-induced increases in GLUT-4 translocation and protein expression of Akt and insulin receptor in the skeletal muscle participated in the improvement of glycemic control in type 2 diabetic patients and rats." (PMID 27832095, 2016). "For example, several subcategories are related to the regulation of adiposity [“Metabolic Disease” (193 genes), “Endocrine System Disorders” (50 genes), “mTOR Signaling” (31 genes), “Insulin Receptor Signaling” (12 genes), and [“Type 2 Diabetes Signaling” (10 genes)]." (PMID 26445145, 2015). "In addition to its key role in the maintenance of glucose homeostasis, insulin and its receptor (INSR) are involved in the development of a number of metabolic conditions, including obesity and type 2 diabetes." (PMID 24434591, 2014). "The significant decrease in insulin receptor expression in islets from patients with type 2 diabetes indicates that blunted insulin signaling in β-cells may make them susceptible to apoptosis." (PMID 22140505, 2011). "Aging and type 2 diabetes mellitus (T2DM) further exacerbate these effects by reducing insulin availability in the brain and impairing insulin receptor signaling at the neuronal level." (PMID 41596611, 2026). "A long-term study of a population with a high prevalence of type 2 diabetes also showed that insulin resistance preceded the onset of type 2 diabetes and was more severe in patients with type 2 diabetes who had insulin receptor variants than in those who did not." (PMID 37108143, 2023). "In addition, some PCOS candidate genes, such as thyroid adenoma associated (THADA) and insulin receptor (INSR), have been associated with metabolic syndrome and impaired glucose regulation in PCOS and type 2 diabetes, suggesting genetic contributions to metabolic dysfunction in women with PCOS." (PMID 35012577, 2022). "INSR LoF is associated with lower TG and HDL levels but may increase the risk of type 2 diabetes." (PMID 34875679, 2022). "Interestingly, diminished insulin-stimulated AKT signaling has been documented in the total lymphocytes of obese individuals, and reduced expression of insulin receptor and downstream signaling molecules have also been reported in patients with type 2 diabetes." (PMID 31756626, 2019). "GAS5 levels are markedly lower in serum samples from individuals diagnosed with type 2 diabetes mellitus (T2DM) and it affects insulin signaling and glucose uptake by binding to UPF1 and regulating insulin receptor expression." (PMID 40563948, 2025). "Studies of type 2 diabetes mellitus (T2DM) in mouse models have shown an increased expression of tyrosine phosphatase 1B, an enzyme that inhibits insulin receptor activity, leading to insulin resistance." (PMID 41155523, 2025). "Type 2 diabetes (T2DM), a chronic metabolic disease, primarily results from an impaired insulin receptor signaling pathway." (PMID 38611920, 2024). "We have demonstrated that GAS5 expression is significantly lower in type 2 diabetes and further demonstrated that GAS5 regulates the expression of insulin receptor." (PMID 35336800, 2022). "miR-144 binds to insulin receptor substrate (IRS1) to control its expression and appears to be a potential therapeutic target for type 2 diabetes treatment in humans." (PMID 35498736, 2022). "Administration of polysaccharides triggers insulin signaling pathways through insulin receptors, and activates the PI3K/Akt pathway by elevating the expressions of the insulin receptor (IRS1), PI3K, and Akt in type 2 diabetic animal models." (PMID 33467194, 2021).
type 2 diabetes (continued). "Furthermore, ROS inactivate the signaling pathway between the insulin receptor and the glucose transporter system, thus acting as a mediator of insulin resistance and β-cell death during the progressive deterioration of glucose tolerance and development of type 2 diabetes." (PMID 32967670, 2020). "On the other hand, the reduced expression of insulin receptor and IRS-1 of the kidney cortex was proposed to contribute to hyperglycemia in high-fat-diet-fed mice or type 2 diabetic rats." (PMID 31137715, 2019). "Protein tyrosine phosphatase (PTP-1B), is a negative regulator of insulin signaling; it inhibits insulin-stimulated tyrosine phosphorylation of insulin receptor (IR), insulin receptor substrate-1 (IRS-1) and is a therapeutic target for type 2 diabetes." (PMID 28608836, 2017). "Because the HMGA1 protein participates in the regulation of the insulin receptor (INSR), the expression of HMGA1-p plays an important role in the onset of type 2 diabetes." (PMID 24312300, 2013). "Additionally, in type 2 diabetes, oxidative damage from glucose may impair insulin receptor tyrosine kinase activity by altering the phosphorylation states of downstream signaling molecules such as insulin receptors and insulin receptor substrates (IRS‐1), leading to insulin resistance." (PMID 40599237, 2025). "The second insulin receptor signaling pathway, the Akt pathway—which is responsible for cell growth and survival, protein synthesis, and inhibition of the glycogen synthase kinase-3β (GSK-3β) enzyme —is also affected by both AD and type 2 diabetes." (PMID 36232867, 2022). "The role of hyperinsulinemia, insulin receptors (IR), and insulin-like growth factor (IGF) on cancer development and progression have attracted scientific interest due to the global epidemics of obesity and type 2 diabetes." (PMID 33572236, 2021). "Protein tyrosine phosphatase 1B (PTP1B), another key enzyme related to type 2 diabetes, works as a negative governor for the insulin signaling pathway by dephosphorylating both the insulin receptor and the downstream insulin receptor substrate proteins." (PMID 34707780, 2021). "The main pathological mechanism of type 2 diabetes was the decrease of insulin receptor sensitivity, that is, IR, resulting in relative lack of insulin." (PMID 32811450, 2020). "Navitoclax treatment has already been shown to improve blood fasting glucose levels in a pharmacological type 2 diabetes model of treatment with the insulin receptor antagonist S961; but it had never been tested with a mouse model of DIO, as presented here." (PMID 32584785, 2020). "Under normal circumstances, the body has a strong tolerance to glucose, while in type 2 diabetes, the body’s insulin receptor is not sensitive, and as such glucose tolerance is decreased." (PMID 31936547, 2020). "In addition to its role in oncology and inflammation, HMGA1 was found to be involved in the transcription of insulin receptor INSR (as a sensor and regulator of insulin signaling), glucose homeostasis and therefore in type 2 diabetes development." (PMID 31762718, 2019). "Nonetheless, circulating transaminases were not increased in InsR+/− mice compared to wt fed an MCD diet resembling what has been observed in IR patients with type 2 diabetes (IR-T2D) and advanced fibrosis." (PMID 31671785, 2019). "Indeed, three members of this subnetwork (i.e. MAPK1, INSR, SOCS3) belong to the Type II diabetes mellitus pathway, which fall into the bigger insulin signaling pathway together with SHC1 and ELK1." (PMID 23885764, 2013). "In type 2 diabetes mellitus (T2DM), AHR activation can interfere with insulin receptor signalling and amplify vascular inflammation." (PMID 40949107, 2025). "The impact analysis also revealed the enrichment of the “Type II diabetes mellitus” pathway resulting from the upregulation of MAPK10 and IRS2 and the downregulation of CACNA1A and SOCS2, a signature that may upregulate the insulin receptor (INSR), PI3K, and insulin resistance." (PMID 36835058, 2023).
type 2 diabetes (continued). "Type 2 diabetes mellitus (T2DM), a common chronic noncommunicable condition in clinic, is featured by physical metabolic disorder and manifested as absolute hyperglycemia and relative insulin insufficiency (caused by inadequate insulin secretion or insulin receptor insensitivity)." (PMID 31977884, 2020). "Reduced hepatic insulin sensitivity in metabolic syndromes, such as type 2 diabetes (T2DM) and non-alcoholic fatty liver disease (NAFLD), may result directly from reduced insulin receptor numbers or indirectly from reduced insulin action via post-insulin receptor signalling pathway genes." (PMID 31284538, 2019). "INSR gene is involved in 12 pathways of which, Type II diabetes mellitus, PI3K-Akt signaling pathway, Insulin signaling pathway (FDR < 0.05) are prominent related to Type 2 Diabetes whereas CCND1 is involved in Jak-STAT signalling pathway apart from PI3K-Akt signaling pathway." (PMID 28761062, 2017). "Indeed, similar opposing trends in GM3 based on fatty acid chain lengths had been observed in the plasma of type 2 diabetes patients and GM3 fatty acyl heterogeneity was proposed to influence lipid raft formation critical for mediating insulin receptor signaling." (PMID 24684787, 2014). "A dysfunctional SOCS3 regulation in myocytes of people with type 2 diabetes is of interest from a broader perspective, as members of the SOCS protein family not only regulate cytokine signaling but also has been shown to inhibit insulin receptor signal transduction." (PMID 22761857, 2012). "Thus, MpHE may alleviate the negative effect of the inflammatory pathways on the insulin receptor signaling and in this way, reverse the memory deficits observed in type II diabetes and AD." (PMID 31291963, 2019). "The combination of insulin and IGF-1 resistance in skeletal muscle in mice, due to expression of a mIGF-1R (mouse IGF-1 receptor), which forms nonfunctioning hybrids with native IR (insulin receptor) and IGF-1Rs (IGF-1 receptors), leads to type 2 diabetes." (PMID 34420367, 2021). "As far as we know, two previous studies in humans, with small sample size (n = 39–40), examined protein or gene expression of the IGF1, IGF2, IGFBP3, INSR, IGF1R and downstream targets IRS1, IRS2 and mTOR in women with or without type 2 diabetes." (PMID 29486734, 2018). "We found that circulating alanine and aspartate aminotransferases (ALT, AST) were not increased in InsR+/− mice compared to wt fed an MCD diet, resembling what has been observed in IR- patients with type 2 diabetes (IR-T2D) with advanced fibrosis." (PMID 31671785, 2019).
Hyperinsulinemia (222 papers, 2005 to 2026). An increased concentration of insulin in the blood. "The insulin phenotype, hyperandrogenism, resistance, and hyperinsulinemia are all brought on by mutations in the insulin receptor gene." (PMID 41370421, 2025). "Insulin Receptor (IR) is a tyrosine-protein kinase on the cell surface, and its over-expression is considered the pathological hallmark of hyperinsulinemia in various cancer cell types." (PMID 39911279, 2025). "Another potential mechanism underlying hyperinsulinism is an impairment of the insulin receptor (INSR)." (PMID 40771275, 2025). "Here the authors use a combination of mouse studies and mathematical modelling to show that loss of beta-cell insulin receptor affects male and female mice differently and can contribute to hyperinsulinemia in the context of glucose stimulation." (PMID 35136059, 2022). "Knockout mouse model of INSR causes hyperinsulinemia andhyperglycemia rapidly following diabetic ketoacidosis." (PMID 36273315, 2022). "For instance, hyperinsulinemia is an independent risk factor for BC and the insulin/insulin receptor (IR) axis is involved in BC growth and metastasis." (PMID 35672854, 2022). "In vitro studies showed that hyperinsulinemia causes insulin resistance via downregulation of insulin receptor phosphorylation." (PMID 36589440, 2022). "Targeted next generation sequencing of the known hyperinsulinism genes identified a novel heterozygous INSR variant p.(Met1180Lys) (c.3539T>A) in the proband, her sister, mother and maternal grandfather." (PMID 31989990, 2020). "Targeted next generation sequencing of the known hyperinsulinism genes identified a novel heterozygous INSR variant p.(Arg1119Gln) (c.3356G>A) in the proband and her mother." (PMID 31989990, 2020). "Targeted next generation sequencing of the known hyperinsulinism genes identified a novel heterozygous INSR variant p.(Arg1191Gln) (c.3572G>A) in the proband and her father." (PMID 31989990, 2020). "In a prolonged hyperinsulinemia state, accumulation of unrecycled INSR is targeted for degradation, resulting in deficiency in INSR and impaired insulin clearance ability." (PMID 31658625, 2019). "This creates a need to examine the insulin-deprivation counterpart to our hyperinsulinemia model system, with the latter a question that would need to addressed in vivo and/or with insulin receptor-deficient mast cells in vitro or in vivo." (PMID 29430572, 2017). "This is in agreement with findings in a hyperinsulinemic mouse model suggesting that reduced insulin receptor efficacy in hyperinsulinemia reduces the capacity to cause a synaptic depression of VTA DA neurons by exogenous insulin induction." (PMID 28719580, 2017). "Specific deletion of the β cell insulin receptor causes a loss of insulin secretion in response to glucose and fasting hyperinsulinemia and impaired glucose tolerance by 6 months of age." (PMID 25946091, 2015). "Patients with INSR mutations or INSR antibodies showed severe hyperglycemia and hyperinsulinemia but normal plasma lipid levels." (PMID 24397589, 2014). "This phenomenon of reduced cells’ response to insulin leads to hyperinsulinemia, which occurs due to genetic polymorphisms; tyrosine phosphorylation of the insulin receptor, insulin receptor proteins, PIP-3 kinase; or abnormalities of GLUT 4 function; and/or environmental factors." (PMID 40943177, 2025). "Hyperinsulinemia may be further caused by a compensatory (secondary) response to insulin receptor resistance." (PMID 41009753, 2025). "During pediatric age, hyperinsulinemia can have a genetic basis, being caused by molecular alterations in insulin secretion or in insulin receptor response; these alterations can be classified as isolated hyperinsulinemia or as part of the clinical presentation of various genetic syndromes." (PMID 38920551, 2024).
Hyperinsulinemia (continued). "The glycemic index has been associated with an increased risk of postmenopausal breast cancer; the insulin receptor has been shown to be elevated in breast cancer, which may explain this tumor’s sensitivity to hyperinsulinemia." (PMID 38814364, 2024). "A potential explanation for this “pathogenic paradox” may be offered by the structural changes in the insulin receptor in response to hyperinsulinemia, which is commonly associated with metabolic syndrome." (PMID 37242206, 2023). "As sequence analysis revealed that the region of exons 9 through 12 of rhesus insulin receptor gene is very similar to that of humans, diabetic monkeys were used to explore the potential association between hyperinsulinemia and alternations in the insulin receptor mRNA splicing in 1994." (PMID 29473878, 2018). "In addition, IL6, IL1B1 and TNF are associated with increased susceptibility to PCOS, and INSR plays a role in compensatory hyperinsulinemia." (PMID 30181771, 2018). "IR-related factors, such as chronic persistent hyperinsulinemia, INSRs, IGF1Rs, INSR/IGF1R hybrids, chronic inflammation, ncRNAs, and microbiota, have been proposed as influential elements in all stages of tumor development." (PMID 40141412, 2025). "Although insulin resistance and hyperinsulinemia are frequently observed in PCOS patients, uncommon mutations in the insulin receptor gene have been discovered in female PCOS patients." (PMID 41370421, 2025). "Chronic sugar consumption induces hyperinsulinemia and disrupts insulin receptor signalling, resulting in reduced cellular responsiveness to insulin." (PMID 40216734, 2025). "Mice transfected with extra copies of the human insulin gene to induce hyperinsulinemia became insulin resistant and showed evidence of insulin receptor downregulation in their livers (Marbán & Roth 1996)." (PMID 40013621, 2025). "Hyperinsulinemia increases insulin receptor signaling and rapid internalization, thereby decreasing the density of plasma membrane receptors." (PMID 40868096, 2025). "Impaired IR function, as seen in hyperinsulinemia, has been associated with reduced growth and lower BMD, whereas excessive insulin receptor signaling, as observed in congenital generalized lipodystrophy (CGL), is linked to accelerated growth and higher BMD." (PMID 40725728, 2025). "Hyperinsulinemia and subsequent insulin receptor dysfunction constitute the core mechanism suppressing hepatic SHBG synthesis and secretion." (PMID 41427050, 2025). "Cancer progression and insulin signaling are directly related, where hyperinsulinemia leads to excessive activation of the insulin receptor (IR), which is highly expressed in cancer cells." (PMID 41007744, 2025). "Hyperinsulinemia can also downregulate signaling of the insulin receptor at the level of effector molecules, disrupting phosphorylation of Insulin Receptor Substrate-1 (IRS-1), Phosphatidylinositol 3-kinase (PI3K), and Protein Kinase B (Akt)." (PMID 41009753, 2025). "T2DM is characterized by hyperinsulinemia as reduced insulin receptor expression and receptor-activating enzymes, leading to the deposition of amyloid beta (Aβ) and Tau proteins." (PMID 39935840, 2025). "Defective insulin receptor signaling due to IR and hyperinsulinemia can lead to a pathological condition resembling diabetic nephropathy, even in the absence of elevated blood glucose levels." (PMID 39072271, 2024). "For therapy of HCC patients with hyperinsulinemia or IR, inhibition of INSR signaling appear to be particularly important." (PMID 38952575, 2024). "Here, we sought to contextualize the role of hyperinsulinemia in aberrant insulin receptor internalization into brain endothelial cells." (PMID 37834116, 2023). "To better contextualize the impact of hyperinsulinemia on internalization, we next sought to determine the mechanism by which the insulin receptor is internalized into MBECs (n = 5–6, N = 2)." (PMID 37834116, 2023).